PER2 (period circadian regulator 2)
Diseases named in the same sentence as PER2 in open-access papers (continued):
Sharing a sentence is not in itself a finding about the gene and the disease.
esophageal cancer (continued). "The results showed that the overexpression of Per2 markedly increased the migration of esophageal cancer cells, which was abolished by transfected with empty plasmids, or knockdown of the HDAC1 gene, of knockdown the E-cadherin gene, respectively." (PMID 26898709, 2016). "In summary, the present data show that human esophageal cancer cells with metastasis express high levels of Per2; Per2 suppresses the expression of E-cadherin in esophageal cancer cells." (PMID 26898709, 2016). "Overexpression of Per2 in the esophageal cancer cells markedly repressed the expression of E-cadherin." (PMID 26898709, 2016). "The results showed that high levels of Per2 were detected in the surgically removed esophageal cancer tissue." (PMID 26898709, 2016). "Overexpression of Per2 in esophageal cancer cells suppressed the expression of E-cadherin and promoted the migratory capacity of esophageal cancer cells." (PMID 26898709, 2016). "In conclusion, our results reveal that in spite of alterations of the expression of clock related genes, PER2 oscillations could be used to improve response to chemotherapy in esophageal cancer." (PMID 33810377, 2021). "Since the level of PER2 expression correlates with apoptosis related genes, it will be important to determine whether PER2 oscillatory expression sensitizes esophageal cancer cells to other anti-cancer therapies and whether PER1 is involved in this process." (PMID 33810377, 2021). "In spite of these alterations, PER2 oscillations still occur in some esophageal cancer cell lines." (PMID 33810377, 2021). "The present data show that one of the circadian proteins, Per2, is highly expressed in esophageal cancer tissue, which is highly correlated with the metastasis of esophageal cancer and the suppression of the expression of E-cadherin in esophageal cancer cells." (PMID 26898709, 2016). "We next observed the biological aspect of Per2 in esophageal cancer cells." (PMID 26898709, 2016). "The results suggest that overexpression of Per2 facilitates the esophageal cancer cell invasion." (PMID 26898709, 2016). "We conclude that Per-2 plays an important role in the esophageal cancer cell metastasis, which may be a novel therapeutic target for the treatment of esophageal cancer." (PMID 26898709, 2016). "In spite of these alterations, PER2 oscillations still occurred in some human esophageal cancer cell lines suggesting that the response to therapy might be enhanced by linking chronotherapy to PER2 expression pattern as a circadian biomarker of interest for personalized chronotherapy." (PMID 38834742, 2024). "HDAC1 is involved in the inhibitory process of E-cadherin induced by Per2; blocking HDAC1 inhibits the migratory capacity of esophageal cancer cells." (PMID 26898709, 2016). "The esophageal cancer cells were negatively isolated by MACS and subjected to RT-qPCR to detect the expression of circadian clock molecule mRNA, including NFIL3, Per1, Per2, Bmal1, Cry1, Cry2, Clock and Npas2." (PMID 26898709, 2016). "To test the inference, we cultured esophageal cancer cells with or without the overexpression of Per2 in a Transwell system." (PMID 26898709, 2016). "We observed that the levels of circadian protein Per2 were significantly increased and E-cadherin was significantly decreased in the tissue of human esophageal cancer with metastasis as compared with non-metastatic esophageal cancer." (PMID 26898709, 2016). "To this end, we assessed the levels of pHDAC1 in esophageal cancer cells with or without Per2 overexpression." (PMID 26898709, 2016). "The results showed that the expression of Per2 was uniquely increased in the esophageal cancer with metastasis, but not in the esophageal cancer without metastasis, nor in the marginal tissue." (PMID 26898709, 2016).
head and neck squamous cell carcinoma (4 papers, 2021 to 2025). A squamous cell carcinoma that arises from any of the following anatomic sites: lip and oral cavity, nasal cavity, paranasal sinuses, pharynx, larynx, and salivary glands. "The loss of PER2 expression is also associated with the development of oral and head and neck squamous cell carcinomas." (PMID 38334624, 2024). "The microRNA miR-3187-3p enhances cell invasion and migration in head and neck squamous cell carcinoma by targeting PER2." (PMID 41142939, 2025). "MicroRNA miR-3187-3p promotes the capacity of migration and invasion of head and neck squamous cell carcinomas (HNSCCs) by targeting PER2." (PMID 38334624, 2024). "Patients with advanced-stage head and neck squamous cell carcinoma exhibited markedly lower levels of PER1, PER2, and PER3 proteins compared to those with early-stage tumors, and higher levels of these proteins were associated with longer overall and recurrence-free survival." (PMID 38813085, 2024).
liver cancer (4 papers, 2016 to 2023). An epithelial or non-epithelial malignant neoplasm that arises from the liver. "Mutation of clock gene Per2 increased nearly fivefold the rate of mice with two or more primary liver cancers as compared to WT exposed to the same DEN dose." (PMID 27494874, 2016). "Here we show that Per2 mutation fostered three critical liver cancer hallmarks, during the initiation stage." (PMID 27494874, 2016). "If the rhythm expression of the PER2 gene oscillates and cannot be adjusted by the circadian rhythm regulation mechanism, it causes circadian rhythm disorders, which lead to many diseases, including liver cancer." (PMID 38074100, 2023). "There was significantly less expression of PER2 protein in liver cancer tissues than in paracancerous tissues (p < 0.05)." (PMID 38074100, 2023). "Based on the clinical and pathological data analysis of patients with liver cancer, PER2 protein expression in liver cancer tissue was significantly related to nerve invasion, Child-Pugh grading, and CNLC staging." (PMID 38074100, 2023). "This study used bioinformatics analysis to determine the potential mechanisms of PER2 in liver cancer." (PMID 38074100, 2023). "In liver cancer tissues, high expression of PER2 protein accounted for 62.5%, and low expression of PER2 protein accounted for 37.5%." (PMID 38074100, 2023). "To analyze the relationship between the circadian rhythm gene PER2 expression level in liver cancer tissues and the clinicopathologic and oncological characteristics, we collected clinical data from 80 patients with liver cancer corresponding to liver cancer tissues." (PMID 38074100, 2023). "As a result, the formation of liver cancers was increased by up to four-fold, six months after the onset of carcinogen exposure, Clock gene Per2 could thus represent a promising target for liver cancer prevention and therapy." (PMID 27494874, 2016). "PER2 expression in HCC significantly correlated with neural invasion, Child-Pugh classification, and China liver cancer staging stage in HCC patients." (PMID 38074100, 2023). "Conversely, the expression levels of ARNTL, NR1D1, PER1, PER2, PER3, PRKAG2, and RORA were not significantly related to the OS of liver cancer patients." (PMID 34149816, 2021).
myocardial infarction (4 papers, 2018 to 2022). Gross necrosis of the myocardium, as a result of interruption of the blood supply to the area, as in coronary thrombosis. "In the present study, given the findings of the investigated SNPs of the CLOCK, ARNTL, and PER2 genes, it was noted that polymorphisms in those clock genes might be an extra risk factor for myocardial infarction." (PMID 32050674, 2020). "Our data suggest that genetic variability in theCRY2 and PER2 genes might be associatedwith myocardial infarction." (PMID 29767668, 2018). "PER2 polymorphisms could be connected with myocardial infarction." (PMID 32050674, 2020). "The genetic variability in the ARNTL, CLOCK, CRY2 and PER2 genes in this study showed that variations in the circadian genes differ between women and men with myocardial infarction." (PMID 34066863, 2021). "This study aimed to examine the potential difference of single nucleotide polymorphisms (SNPs) of the circadian rhythm genes ARNTL, CLOCK, CRY2 and PER2 in women and men with myocardial infarction." (PMID 34066863, 2021). "The present study was aimed at searching for a potential correlation between the SNPs of the CLOCK, ARNTL, and PER2 genes in patients with myocardial infarction." (PMID 32050674, 2020). "Furthermore, probably, analyzed polymorphisms in the ARNTL, CRY2, and PER2 genes are not functionally associated with myocardial infarction." (PMID 34066863, 2021). "Some authors found Per2-mutant mice had less severe injury in ischemia/reperfusion and nonreperfused myocardial infarction than control mice." (PMID 35743288, 2022).
osteoarthritis (4 papers, 2014 to 2024). A noninflammatory degenerative joint disease occurring chiefly in older persons, characterized by degeneration of the articular cartilage, hypertrophy of bone at the margins and changes in the synovial membrane. "This research aimed to explore the role of period circadian clock 2 (Per2) in the evolution of osteoarthritis (OA) and the relevant mechanisms." (PMID 32426819, 2020). "In addition, Per2 facilitates NHAC-kn inflammation in osteoarthritis by heightening the PTEN level and dampening the PI3K/Akt expression." (PMID 34554926, 2021). "Interestingly, in mouse model of osteoarthritis (OA), circadian oscillations of PER2 transcription are reported to be significantly reduced in cartilage from aged mice, and the robust oscillations of PER2 transcription are confirmed in cartilage from juvenile mice." (PMID 24901009, 2014).
Parkinson disease (4 papers, 2013 to 2025). A progressive degenerative disorder of the central nervous system characterized by loss of dopamine producing neurons in the substantia nigra and the presence of Lewy bodies in the substantia nigra and locus coeruleus. "Core clock genes, particularly BMAL1, PER2, and REV-ERBα, exhibited disease-specific alterations in expression patterns in both central and peripheral tissues of patients with AD, Parkinson’s disease (PD), and Huntington’s disease (HD)." (PMID 40363695, 2025). "We have now consistently seen a dissociation between normal PER2 rhythms in the SCN and reduced SCN output in three different models of neurodegeneration: the BACHD mouse model, a mouse model of Parkinson’s Disease, and in middle-aged mice." (PMID 23936129, 2013).
renal carcinoma (4 papers, 2014 to 2023). A carcinoma arising from the epithelium of the renal parenchyma or the renal pelvis. "Considering that Per2 is reported to have tumor-suppressor properties, it is possible that HIF1α increases Per2 transcriptional activity thereby inhibits tumor proliferation in contrast to the previous finding that HIF-mediated gene pathway is the main risk-factor of tumor growth in renal cancer." (PMID 25333958, 2014). "Considering the results that the Per2 circadian rhythm was shown only in Caki-2 cells, which contained BMAL1, CLOCK, and HIF1α protein, it is possible that HIF1α is related to the Per2 circadian rhythm in renal cancer cell lines." (PMID 25333958, 2014). "In this study, we measured the levels of Per2 promoter activity and mRNA in eight renal cancer cell lines after dexamethasone treatment." (PMID 25333958, 2014). "HIF-1A promotes the amplitude of PER2 rhythms in renal cancer." (PMID 31014368, 2019). "However, further investigation is required to determine the molecular mechanisms of HIF1α-induced enhancement of Per2 circadian rhythms and differences between Caki-2 and other renal cancer cell lines." (PMID 25333958, 2014). "Therefore, we should investigate the detailed molecular mechanisms of Per2 as potentially important targets for renal cancer therapy and clarify the effect of HIF induced Per2 upregulation on tumor progression in renal cancer in future study." (PMID 25333958, 2014). "This suggested that both BMAL1/CLOCK and HIF1α may be related to the circadian expression of Per2 in renal cancer cell lines." (PMID 25333958, 2014). "In renal cancer, altered expression of the Per2 gene is reportedly involved in disease onset and progression, but the molecular mechanism responsible remains unclear." (PMID 25333958, 2014). "However, the expression levels of PER1, PER2 in KIRC and CRY2 in KICH were significantly increased in tumor tissues, and they suggested subsequent in-depth investigation of the mechanisms underlying circadian abnormalities in these three renal carcinomas." (PMID 34977153, 2021). "In this study, the rhythmic expression of the Per2 gene was not detectable in renal cancer cell lines, with the exception of Caki-2 cells." (PMID 25333958, 2014). "All renal cancer cell lines expressed CLOCK and CRY1 protein, but did not express PER2 protein." (PMID 25333958, 2014). "Furthermore, all renal cancer cell lines expressed CRY1 protein, but did not express PER2 protein." (PMID 25333958, 2014).
rheumatoid arthritis (4 papers, 2018 to 2025). A chronic, systemic autoimmune disorder characterized by inflammation in the synovial membranes and articular surfaces. "PER2 isdownregulated by the LPS-induced inflammatory response in synoviocytesin rheumatoid arthritis and is implicated in disease susceptibility.Mol." (PMID 39440312, 2024). "PER2 is associated with both rheumatoid arthritis and OA, suggesting that altered PER2 expression may be a risk factor for rheumatoid arthritis and that its expression may be affected by inflammation." (PMID 40588525, 2025). "Further, immunoblotting analysis showed the Per2 protein expression was inhibited in LPS-treated rheumatoid arthritis synovial cells." (PMID 32426819, 2020). "For the further understanding of circadian manifestation in rheumatoid arthritis, we showed that the expression of Bik, as well as Per2, was gradually increased from 8 h until 24 or 32 h, and MTX was significantly effective in situations when Per2 and Bik were highly expressed." (PMID 29566767, 2018).
steatosis (4 papers, 2013 to 2025). Increased lipid within the cytoplasm of cells. "Exogenous melatonin has a protective effect: it reduces necrosis and steatosis, partially restores circadian genes (Per2 and BMAL1), and normalizes biochemical parameters (ALT, AST, and glucose)." (PMID 41614811, 2025).
Stroke (4 papers, 2020 to 2025). Sudden impairment of blood flow to a part of the brain due to occlusion or rupture of an artery to the brain. "The box plot illustrates that in the stroke group, the expression levels of Spp1 and Cav1 were significantly elevated, whereas the expression level of Per2 was reduced." (PMID 40292254, 2025).
thyroid cancer (4 papers, 2020 to 2024). "Thus, PER2 ablation in thyroid cancer could contribute more significantly to processes associated with early stages of tumorigenesis, which involve cell proliferation." (PMID 36284088, 2022). "PER2 lack activates AP-1 through JNK signaling and promotes age-related thyroid hyperplasia disease and thyroid cancer." (PMID 39267721, 2024). "Downregulation of PER2 was reported for follicular and poorly differentiated cancer (FTC and PDTC), while upregulation was found in a study of unspecified thyroid cancer (TC)." (PMID 37489438, 2023).
viral infection (4 papers, 2013 to 2022). "Strong viral infection (eGfp mRNA expression) was observed in all brains that received the AAV-Per1/Per2 shRNA+eGfp microinfusion." (PMID 30627637, 2018). "Viral infection (300 HAU/ml) also significantly reduced the amplitude and increased the period of PER2::LUC expression in lung explants." (PMID 25923474, 2015).
Alcohol Use Disorders (3 papers, 2013 to 2024). "Studies with mice have shown that alcohol abuse may lead to an increase in the expression of the Per2 gene that encodes the period circadian regulator Per2." (PMID 38674014, 2024). "At age 19 years, 268 young adults (126 males, 142 females) were genotyped for PER2 rs56013859 and were administered a 45-day alcohol timeline follow-back interview and the Alcohol Use Disorders Identification Test (AUDIT)." (PMID 23533602, 2013). "Clinical investigations report reduced baseline Clock mRNA levels in patients with alcohol use disorder, as well reduced baseline mRNA levels of circadian proteins BMAL1, Per1, Per2, Cry1, and Cry2." (PMID 35456507, 2022).
Alzheimer disease (3 papers, 2020 to 2024). A progressive, neurodegenerative disease characterized by loss of function and death of nerve cells in several areas of the brain leading to loss of cognitive function such as memory and language. "A third pathway affected by calpain-1 deletion is the Alzheimer’s disease pathway, with significant decrease in IDE and PER2." (PMID 32328086, 2020).
Arthritis (3 papers, 2014 to 2024). Inflammation of a joint. "First, we confirmed the influence of arthritis on clock gene expression using wild type (WT) mice that had been administered anticollagen antibody and LPS and PER2 protein levels in the synovium were monitored." (PMID 24901009, 2014). "PER2 is usually expressed at night, but in the arthritis model PER2 was highly expressed in the morning." (PMID 24901009, 2014). "Since circadian clock genes were reported to be closely related to the pathogenesis of arthritis and excessive expression of Per2 could induce apoptosis, we examined the effect of MTX on expression of Per2, Bmal1, Clock, and Cry1 that were regarded as “core” clock genes." (PMID 29566767, 2018).
cholestasis (3 papers, 2016 to 2022). Impairment of the bile flow caused by obstruction within the liver, or outside the liver in the bile duct system. "The PER2 gene is also an important component of liver circadian system and the deficiency of PER2 induces the liver injury and fibrosis during cholestasis." (PMID 26843619, 2016). "Moreover, Per2 is also associated with hepatic functions; for example, Per2 knockout mice showed more severe liver fibrosis, cholestasis, or infarction under toxic conditions than wild-type mice." (PMID 35910841, 2022). "In the bile duct ligation model of Per2-null mice Per2 played a protective effects of cholestasis, atorvastatin repressed the expression of this feedback genes may increase the risk of Liver injury." (PMID 28533986, 2017).
chronic obstructive pulmonary disease (3 papers, 2018 to 2025). A chronic and progressive lung disorder characterized by the loss of elasticity of the bronchial tree and the air sacs, destruction of the air sacs wall, thickening of the bronchial wall, and mucous accumulation in the bronchial tree. "Imbalances in autophagy levels resulting from disrupted oscillations and the expression of clock genes such as PER1 and PER2 are implicated in the pathogenesis of chronic obstructive pulmonary disease (COPD)." (PMID 41234362, 2025). "The expression levels of clock proteins such as BMAL1 and PER2 are reduced in inflamed lung tissue and peripheral blood mononuclear cells in patients with chronic obstructive pulmonary disease." (PMID 29534090, 2018). "The same study observed that the mRNA and protein levels of BMAL1, PER2, CRY1, and REV-ERBα were reduced in the peripheral blood mononuclear cells (PBMCs), lung tissue, and sputum cells of smokers and patients with chronic obstructive pulmonary disease (COPD) compared to non-smokers." (PMID 40255337, 2025).
cognitive decline (3 papers, 2021 to 2024). "We aimed to assess the association of PER2 C111G polymorphism with cognitive functions in subjective cognitive decline (SCD)." (PMID 33919572, 2021).
coronary artery disease (3 papers, 2014 to 2025). "In aorta, we identified perturbations in a number of TFs involved in circadian clock regulation (CRY1, CRY2, PER2), vascular inflammation (PPARG, NR3C1), and those linked in coronary artery disease, including the estrogen receptor, ESR2." (PMID 39896461, 2025).